CCL2 (C-C motif chemokine ligand 2)
Diseases named in the same sentence as CCL2 in open-access papers (continued):
Sharing a sentence is not in itself a finding about the gene and the disease.
glioma (continued). "Studies have demonstrated that GAMs were recruited to sites of gliomas via interaction between CCL2/MCP-1 which are basically generated by glioma cells as well as its receptor CCR2 which is secreted by GAM and by a CCL7/MCP-3-CCR1/CCR2/CCR3-crosstalk." (PMID 35419058, 2022). "As for cytokines, CCL2, referred to as monocyte chemoattractant protein-1(MCP-1), is an important cytokine characterized as a glioma-cell-derived monocyte chemotactic factor." (PMID 35883585, 2022). "The lack of effect observed following the implantation of individual CCL2 or CCL7 knockdown gliomas suggested a potential chemokine ligand redundant mechanism utilized by the KR158B cells to recruit CCR2+/CX3CR1+ cells to the TME." (PMID 36685592, 2022). "The Spearman correlation analysis results suggested that the immune marker sets of Treg (FOXP3, CCR8, TGFβ1), TAM (CCL2, CD68, IL-10), and MDSC (CD33, ITGAM, FUT4) were significantly associated with the PROS1 expression in glioma." (PMID 36685506, 2022). "Our analysis here only included one cell line, but previous studies found microglia secrete most of the CCL2 after being recruited by low levels of glioma-derived CCL240." (PMID 35906273, 2022). "In the glioma mouse model, celecoxib treatment decreased protein expression and mRNA levels of Ccl2, CxcL10, and Cxcr3, both in the tumoral and peri-tumoral tissue." (PMID 35269652, 2022). "The study found that CCL2 was significantly upregulated in TMZ-resistant glioma cells compared to the parental cell lines." (PMID 36077785, 2022). "CCL2 released from glioma is a critical chemokine for TAMs and simultaneously triggers IL-6 release from microglia, thereby promoting the invasiveness of glioma cells." (PMID 35600367, 2022). "A 44-plex cytokine array (Luminex) revealed glial cells are a major source of pro-tumorigenic CCL2 while glioma cells express CXCL1 and CXCL8." (PMID 35906273, 2022). "LIF and CCL2 have been found to be involved in glioma 39, 55, 56, but their relationships with molecular subtypes of GBM have not yet been described." (PMID 34987659, 2022). "Gliomas produces cytokines that can recruit MDSCs (i.e. CCL2, CXCL8, SDF-1, CXCL2), as well as cytokines that induce MDSCs expansion (i.e., IL-6, PGE2, IL-10, GM-CSF)." (PMID 36186781, 2022). "C-C motif chemokine ligand 2 (CCL2) produced by CXCR4+ tumor-associated microglia M1 can recruit the CC chemokine receptor 4 (CCR4)+-expressing Treg cells and MDSCs to gliomas." (PMID 33918635, 2021). "As expected, the IHC analysis showed that CCL2 was also upregulated in glioma tissues compared with normal tissues; the qPCR measurement showed the abundant expression of CCL2 in U87, U251, U373, and SHG-44 cells." (PMID 33414423, 2021). "Diosmin repressed expression of CCL2 mRNAs and protein in glioma cells which suggests that this protein is likely downstream to the diosmin target." (PMID 34638796, 2021). "Next, we implemented a set of cell phenotype tests that are similar to MEX3A-related studies on SHG-44 cells transfected with shCCL2 or shCtrl to verify the role of CCL2 in glioma." (PMID 33414423, 2021). "In this study, CXCL10 and CCL2 chemokines displayed the most significant effects on the attraction and migration of glial tumor cells in vitro, as well as in vivo in the F98-Fischer rat model." (PMID 34830041, 2021). "Similar inhibitory effects of CCL2 knockdown on glioma cell growth were observed by Celigo cell counting assay." (PMID 33414423, 2021). "Here, we provide further evidence by in vitro assays that CCL2 is involved in the migration and invasion of glial tumor cells." (PMID 34830041, 2021). "CCL2 was first identified from the supernatant of glioma cells and originally referred to as monocyte chemoattractant protein-1 (MCP-1) based on its chemotactic activity for monocytes." (PMID 33803414, 2021). "Altogether, the results demonstrated that CCL2 not only has a co-expression profile with MEX3A but also possesses similar regulatory effects on glioma with MEX3A." (PMID 33414423, 2021).
glioma (continued). "Glioma cells secrete CCL2, which induces IL-6 secretion in microglia thereby increasing glioma invasiveness." (PMID 34503065, 2021). "Herein, we verified that, similar with MEX3A, CCL2 was also upregulated in glioma tissues relative to normal tissues." (PMID 33414423, 2021). "EGFR and epidermal growth factor variant III (EGFRvIII) cooperate to induce macrophage infiltration via upregulation of the chemokine CCL2, and KRAS was a critical signaling intermediate for the EGFR- and EGFRvIII-induced expressions of CCL2 in glioma cells." (PMID 34071306, 2021). "CCL2 produced by both glioma cells and GAMs, has also been shown to be essential for the recruitment of Treg cells and myeloid-derived suppressor cells, which act as drivers of the immune-suppressive phenotype typical of these tumors." (PMID 33802571, 2021). "PD-L1 is PD-1 ligand and their interaction is required for inhibiting T cells and glioma-derived CCL2 recruits regulatory T cells." (PMID 34372858, 2021). "Lower levels of tumor-infiltrating macrophages, including CD68+ (~30%), F4/80+ (~50%), and CD11c+ macrophages (~50%), were identified in FUCA1-downregulated glioma tissues, and CCL2/CCL5 neutralizing Abs blocked this effect." (PMID 34071306, 2021). "In particular, MCP-1/CCL2 is believed to be a major contributor in microglia recruitment to gliomas and others brain tumor metastases." (PMID 33917013, 2021). "The CCL2/CCR2 signaling axis is particularly relevant as a therapeutic target since its downregulation inhibits glioma development." (PMID 34359681, 2021). "Another suggested regulator for MDSCs is accumulation of CCL2, which when released by glioma cells recruits CCR2-expressing MDSCs in addition to activating Tregs." (PMID 33766119, 2021). "WB results of intracranial glioma tissues further show that, compared to Control group, the expression of PD-L1, CCL2 and TDO2 was increased in CYB561D2 infected gliomas while co-infection with DN-STAT3 fully rescued this effect." (PMID 34372858, 2021). "The mechanistic research of this study revealed CCL2 as a potential downstream target of MEX3A in the regulation of glioma." (PMID 33414423, 2021). "Lacking CCR2 solely on tumor microenvironmental cells leads to enhanced tumor progression, whereby high numbers of GAMs infiltrate gliomas independently of the CCR2/CCL2 signal." (PMID 34071306, 2021). "Previous evidence indicates that CCL2 in the glioma microenvironment promotes the recruitment of Tregs and myeloid-derived suppressor cells (MDSCs)." (PMID 34778248, 2021). "Previously, the function of CCR2/CCL2 signal for glioma biology was investigated by focusing on its ligand CCL2." (PMID 32668709, 2020). "Still, 70% of IBA1+ cells were recruited into the glioma area independently of the CCR2/CCL2 signal." (PMID 32668709, 2020). "In the glioma microenvironment, CCL2, released by macrophages and microglia, is crucial for attracting myeloid-derived suppressor cells (MDSCs) and Tregs thus creating an immunosuppressive/tumor supporting environment." (PMID 33066172, 2020). "Under these conditions, not only the recruitment of TAMs is inhibited but also the attraction of regulatory T cells via CCR4 and the autocrine mechanism on glioma cells, expressing CCL2 and CCR2, is interrupted." (PMID 32668709, 2020). "CCL2 depletion led to a significant recruitment of cytotoxic T cell in the tumor microenvironment, which resulted in glioma growth suppression." (PMID 32765498, 2020). "In 19 GBM patients where CD4/CD25bright cells were isolated, Tregs migrated preferentially to glioma conditioned media and was reversed by using a CCL-2 blocking antibody." (PMID 31973059, 2020). "We found that knockdown of Rab27a led to a marked increase in expression of CCL2, a cytokine vital in mediating macrophage, micoglia, and regulatory T cell infiltration in glioma." (PMID 33282910, 2020).
glioma (continued). "In a high-throughput screening cell-based S100B promoter-driven luciferase reporter assay, duloxetine was identified to inhibit S100B and CCL2 production in a mouse glioma model." (PMID 32722137, 2020). "This indicates that the recruitment of TAMs is strictly related to CCL2 secretion during glioma tumorigenesis." (PMID 32456359, 2020). "It was shown that increased expression of CCR2, a receptor for CCL2, also stimulates the recruitment of TAMs and fibroblasts at the primary tumors, where they enhance invasion, angiogenesis, and metastasis of glioma and other cancers." (PMID 32456359, 2020). "To analyze which cells co-localized with CCL2+ or CXL10+ cells in the glioma model, we used the stem cell marker Nestin, a microglia marker Iba-1, and the M1- and M2-type monocyte macrophage markers CD16 and CD163, respectively." (PMID 32943658, 2020). "One study illustrated that glioma-derived CCL2 acts upon CCR2-bearing microglia to produce IL-6, which then stimulates gliomas." (PMID 32194542, 2020). "It has been reported that infiltration of T lymphocytes into the brain of patients with glioma coincides with CCL2 expression in GFAP+ astrocytes." (PMID 32098620, 2020). "Knockdown of CCL2 via siRNA inhibited cell proliferation and angiogenesis in the glioma cell line U251 in vitro while overexpression in a U87 glioma cell line increased invasiveness, dependent on presence of CCR2-expressing microglia." (PMID 33282910, 2020). "In particular, glioma cells recruit GAMs through the monocyte chemoattractant protein MCP-1 (or CCL2)." (PMID 33153019, 2020). "In this study, we confirmed the role of Rab27a in the release of small EVs in glioma in vitro and showed that knockdown of Rab27a resulted in reduced cell viability and increased expression of CCL2." (PMID 33282910, 2020). "An absence of Tregs causes a phenotypic shift in macrophage populations toward M1, while macrophages and microglia produce CCL2 within the glioma microenvironment, a chemokine that is critical for the recruitment of Treg and M-MDSCs." (PMID 32240177, 2020). "Targeting the ligand of CCR2, CCL2, in prostate cancer and glioma led to a reduction of tumor growth and prolonged survival." (PMID 32668709, 2020). "In the present study, we identified CCL2 in GSCs, the mouse glioma model, and in the culture medium in the presence of a large number of dead cells." (PMID 32943658, 2020). "Glioma cells initially secrete low levels of CCL2 to chemotactically attract microglia cells, which increase CCL2 generation in the tumor environment." (PMID 33585220, 2020). "On the other hand, in the mouse glioma model, the high protein and mRNA level of Ccl2, Cxcl10 and Cxcr3 were decreased by celecoxib." (PMID 32943658, 2020). "We confirmed the expression and secretion of a large number of inflammatory cytokines in IL-33+ glioma cells and, with the exception of CCL2, indicate regulation of these genes by nuclear IL-33." (PMID 33020472, 2020). "The amplified secretion of CCL2 by microglial cells recruits even more microglial cells into the tumor, stimulating the progression and development of the glioma." (PMID 33585220, 2020). "Inhibiting CCL2 activity in mice studies (GL261 glioma and xenograft of human U87 models) with relevant antibodies has been shown to reduce infiltration and ultimately prolong survival." (PMID 32765498, 2020). "Even if CCL2 is believed to be the major recruiter of TAMs in gliomas, other factors like CX3CL1, CXCL12, M-CSF and GM-CSF can mobilize TAMs into brain tumor areas, and become relevant under Ccr2-deficiency." (PMID 32668709, 2020). "RT-qPCR showed a nearly twofold upregulation of CCL2 mRNA in shRab27a glioma cells (independent t-test, p < 0.0001)." (PMID 33282910, 2020). "GAMs-attracting chemokines and cytokines secreted by glioma cells, which suppress immune cells, include CCL2, CXCL12, CSF-1, and MIF." (PMID 32194542, 2020).
glioma (continued). "It has also been reported that pathologic grades of glioma are significantly related with expression levels of CCL2." (PMID 31207928, 2019). "U87 glioma cells express several chemokines (CCL2, CCL20, CXCL1, CXCL2, CXCL8, etc.), among which IL-8 is the most abundant after radiation." (PMID 31488817, 2019). "Chemokine (C-C motif) ligand 2 (CCL2) is one of the main chemoattractant for macrophages and has been implicated in glioma angiogenesis." (PMID 31366997, 2019). "CCL2 that is produced by the glioma microenvironment is essential for the recruitment of regulatory T cells and myeloid-derived suppressor cells." (PMID 31366997, 2019). "Celecoxib, a Cox2 inhibitors, was shown to decrease MDSC recruitment and increased CD8+ T cell tumor infiltration in gliomas and colon carcinoma by decreasing CCL2 production." (PMID 31447834, 2019). "In a GEM mouse model of glioma, it has been recently demonstrated that CCL2-CCR2 interaction plays a critical role in the recruitment of M-MDSCs to the tumor site, in which CCL2 is produced by GAMMs within the glioma microenvironment." (PMID 31225500, 2019). "Specifically, the glioma growth is induced by the IL-6 levels, which are produced by microglial cells under stimulation of glioma-released CCL2 that acts upon CCR2 in microglia." (PMID 30123112, 2018). "Other chemokines released by glioma cells, such as CCL2, have been reported to play a role in the recruitment of GAMs within the tumor mass, but do not contribute to their phenotypic changes." (PMID 30542347, 2018). "In the case of GBs, glioma cells are able to stimulate GAMs to produce immunosuppressive molecules, such as IL-10, metalloproteinases (MMPs), chemokines as monocyte chemotactic protein-1 (CCL2), and ARG-1, that stimulate the tumor growth." (PMID 30123112, 2018). "CCL2 is the key chemokine that recruits myeloid-derived cells to the tumor microenvironment in glioma." (PMID 30333036, 2018). "In summary, recruitment and subsequent M2 polarization of GAMs has been shown to be mediated by multiple glioma cell-derived chemoattractants such as MCP-1 (CCL2), SDF-1 (CXCL12), M-CSF (CSF-1), GM-CSF, and EGF." (PMID 29389898, 2018). "The CCL2 was firstly detected in glioma cell supernatants and confirmed to be a chemoattractant protein for immune cells in vitro." (PMID 30123112, 2018). "CCL2 increases the infiltration of GAMs and the CCL2 expression is related to the World Health Organization (WHO) grade of gliomas." (PMID 29389898, 2018). "Upregulated IL-6 production in microglia stimulates glioma invasiveness, and it was suggested that the CCL2/CCR2/IL-6 loop represents a potential target to interfere with glioma invasion." (PMID 29258556, 2017). "Macrophages and microglia within the glioma microenvironment produce CCL2, which is critical for recruiting regulatory T cells (Treg) and myeloid-derived suppressor cells (MDSC)." (PMID 28587280, 2017). "Decrease of CCL2 can be empaires with reduction of the infiltration of MDSC and tumor-associated macrophages (TAM) into the glioma site." (PMID 28499389, 2017). "CCL2 is another factor released from glioma cell lines and acts on the CCL2 receptor (CCR2) expressed on microglia." (PMID 29410971, 2017). "Purinergic signaling related genes such as GPR17, VEGFA and CCL2 are involved in inflammation leading to glioma growth." (PMID 27323413, 2016). "Glioma cells produce chemotactic factors, such as CCL2 and M-CSF, resulting in the recruitment of microglia and peripheral blood-derived macrophages." (PMID 25978454, 2015). "IL1β from inflammatory monocytes has a paracrine effect on glioma cells and induces increased levels of CCL2 in tumor cells, which in turn has a paracrine effect on inflammatory monocytes, resulting in increased infiltration." (PMID 25987130, 2015).
glioma (continued). "Other chemokines and cytokines known to be involved in glioma progression, such as CCL2, CXCL10 and IL-6, are selectively upregulated in the glioma-bearing hemisphere, and these increases are strongly reduced in EE mice." (PMID 25818172, 2015). "Systemic administration of neutralizing antibody against CCL2 significantly inhibits the infiltration of microglia/macrophages in mice bearing gliomas." (PMID 23864876, 2013). "Astrocytes surrounding human glioma biopsies secrete CCL2, a macrophage and T cell recruiting chemokine, with a strong positive correlation between CCL2 expression and T cell infiltration." (PMID 23596394, 2013). "Both ASA-treated and Cox2−/− mice demonstrated a reduction in MDSCs and their CCL2-mediated accumulation in the glioma." (PMID 24202450, 2013). "ASA treatment also reduced monocyte chemoattracting protein (MCP)-1, also known as CCL2 (C-C motif ligand 2), in the glioma as well as the number of MDSCs in both bone marrow and the glioma." (PMID 24202450, 2013). "Among chemokine pathways involved in TAM chemoattraction, CCL2 (monocyte chemotactic protein-1 (MCP-1)) was among the first identified in gliomas." (PMID 23864876, 2013). "Although CCL2 expression can be induced by a variety of stimuli and cytokines, mechanisms responsible for its baseline expression by gliomas are being studied." (PMID 23864876, 2013). "Systemic blockade of CCL2 exhibited reduced infiltration of MDSC and tumor-associated macrophages (TAM) into the glioma site and prolonged survival in murine models." (PMID 24202450, 2013). "Since CD3+ T-cells seem to respond to CCL2 in the inflamed parenchyma in the human glioma and monkey brain, we analyze their ability to express the CCL2 receptor (CCR2) in their cell surface." (PMID 22319587, 2012). "More recently, Ccl2 has also been implicated in recruitment of MDSC to transplanted tumors and to an autochthonous glioma in mice." (PMID 23173060, 2012). "Detailed confocal co-localization analysis demonstrated that the CCL2+ cells were also astrocytes in LPS-induced infiltration in mice, similar to the situation observed in human gliomas and monkey brain." (PMID 22319587, 2012). "CCL2 expression has been related with the aggressiveness of the glioma and, in fact, the use of CCL2 neutralizing antibodies has been suggested as a possible strategy for their treatment." (PMID 22319587, 2012). "CCL2 is produced by glioma tumour cells and has both direct and indirect inhibitory effects, among which attraction of T reg cells." (PMID 20953324, 2010). "After irradiating the glioma tumour cells, the NPs could be directed toward the chemokine (CC motif) ligand 2 (CCL2), which is greatly expressed through radiation-induced tropism." (PMID 40002469, 2025). "Notably, our findings reveal that naringenin treatment reduced CCL2 mRNA transcription, suggesting its potential to restrain glioma development and progression." (PMID 40149846, 2025). "In addition, both in vivo and in vitro models of glioma show that Fusobacterium nucleatum promotes glioma proliferation and upregulates CCL2, CXCL1, and CXCL2 levels." (PMID 39660865, 2025). "Moreover, we found that R-2HG regulates the glioma microenvironment by decreasing IL-6, CCL2, CXCL10, and MMP-14 in microglia." (PMID 41367876, 2025). "HBS-101, a novel midkine inhibitor, reduced optic nerve proliferation, normalized RNFL thickness, and decreased the expression of tumor (Neu4, Gpr17) and TME (Ccl2, Ccl3, Ccl4, Ccl5) genes, supporting its continued development as a targeted therapy for pediatric NF1-associated glioma." (PMID 41497446, 2025). "Furthermore, the analysis revealed correlations between CCL2 expression and clinical features, immune cell infiltration patterns, and enrichment of specific pathways, highlighting the complex correlation between CCL2 signaling and glioma progression." (PMID 39030882, 2024). "After blocking TREM1, glioma-derived TAMs expressed less levels of IL-6, IL-8, CCL2 and CCL8." (PMID 38370418, 2024).